TMPRSS4 (transmembrane serine protease 4)
Diseases named in the same sentence as TMPRSS4 in open-access papers (continued):
Sharing a sentence is not in itself a finding about the gene and the disease.
lymph node metastasis (2 papers, 2013 to 2022). "In conclusion, our study provides evidence that TMPRSS4 expression is associated with lymph node metastasis, tumor size, and histological grade in TNBC patients, and also is an independent prognostic factor for TNBC." (PMID 23857060, 2013). "Our study provides evidence that TMPRSS4 expression is associated with lymph node metastasis, tumor size, and histological grade in TNBC patients, and also is an independent prognostic factor for TNBC." (PMID 23857060, 2013). "In multivariate analysis, only lymph node metastasis and TMPRSS4 expression were the independent prognostic factors for OS and DFS in TNBC." (PMID 23857060, 2013). "High expression of TMPRSS4 was significantly correlated with lymph node metastasis, histological grade, and tumor size." (PMID 23857060, 2013). "In regard to RFS, the univariate analysis revealed that the gender, Lauren’s pathological type, TMPRSS4, tumor size, deeper tumor invasion, lymph node metastasis, venous invasion, lymphatic invasion, invasion type, and stages of tumor were all significant prognostic factors for RFS." (PMID 34379296, 2022).
papillary thyroid cancer (2 papers, 2022). "Notably, our study evaluated only carcinomas which originate from the thyrocytes, and TMPRSS4 was more highly expressed in tall cell variant of papillary thyroid carcinoma (PTC) than in classical and follicular PTC." (PMID 36380313, 2022). "Moreover, miR-1258 was reported to restrain cell proliferation, migration, and invasion in papillary thyroid cancer via regulating transmembrane protease serine 4 (TMPRSS4)." (PMID 35582196, 2022).
prostate adenocarcinoma (2 papers, 2016 to 2021). "To determine whether TMPRSS4 expression correlates with SLUG, TWIST1, and stemness-related factors expression in human cancers, we analyzed TCGA-generated prostate adenocarcinoma data (TCGA, Firehose Legacy and TCGA, Cancer Cell 2010 studies)." (PMID 34809669, 2021).
autism (1 paper, 2024). Persistent deficits in social interaction and communication and interaction as well as a markedly restricted repertoire of activity and interest as well as repetitive patterns of behavior. "Variations in the genes TMPRSS4, TRPC4, and PCDH9 were consistently linked to autism across the two independent samples, highlighting the role of calcium signaling and cell adhesion molecules in the risk of autism-related disorders." (PMID 39766876, 2024).
Bartter syndrome (1 paper, 2019). "CAP2/Tmprss4 might represent an interesting pharmacological target in diseases modulating diuresis, such as NDI or Bartter’s syndrome, especially in a context of low dietary potassium intake." (PMID 31863073, 2019).
bladder tumor (1 paper, 2020). "In summary, this result elucidates that there is a high possibility of the participation of CORO1C and TMPRSS4 in the bladder tumor cell EMT based on the opposite effects, which suggested their different roles during disease metastatic course." (PMID 32695668, 2020).
breast tumors (1 paper, 2025). "Additionally, S100A14 and TMPRSS4 were both hypomethylated and upregulated in breast tumors." (PMID 40943642, 2025).
cervical squamous cell carcinoma (1 paper, 2022). A squamous cell carcinoma arising from the cervical epithelium. "Among them, decreased TMPRSS4 predicted a poor prognosis for BLCA, cervical squamous cell carcinoma (CSCC), LUSC, and THCA." (PMID 36380313, 2022).
esophagus cancer (1 paper, 2022). "Similarly, we observed statistically significant positive correlation for the expression of TMPRSS2 and TMPRSS4 genes in pancreatic and esophagus cancer cell lines (d p-values < 0.05 and R-values 0.359 and 0.521, respectively)." (PMID 35970857, 2022).
Hyperglycaemia (1 paper, 2025). "Hyperglycaemia, instead of hyperinsulinaemia and hyperlipidaemia, can significantly induce the expression of SARS‐CoV‐2 entry factors (Ace2, Tmprss2, Tmprss4, Furin and Nrp1) in liver cells, but not in lung and pancreatic cells, which is attenuated by mTOR inhibition." (PMID 40442985, 2025).
Hyperinsulinemia (1 paper, 2021). An increased concentration of insulin in the blood. "ENaC channel activity is stimulated by insulin in the kidney; this may be an important link between kidney injury and the hyperinsulinemia observed in PCOS, enhanced by dysregulation in TMPRSS4." (PMID 33922918, 2021).
hypersensitivity pneumonitis (1 paper, 2018). Hypersensitivity pneumonitis (HP) is a pulmonary disease with symptoms of dyspnea and cough resulting from the inhalation of an antigen to which the subject has been previously sensitized. "We first evaluated by real-time qPCR the expression of TMPRSS4 in lung samples from IPF patients (n = 7) compared with normal tissues (n = 4) and hypersensitivity pneumonitis (HP, n = 6)." (PMID 29529050, 2018).
pancreatitis (1 paper, 2016). Inflammation of the pancreas. "Importantly, expression of three of the five genes, POSTN, SERPINB5 and TMPRSS4, apparently increases gradually from healthy pancreas to pancreatitis and further rises between pancreatitis and PDAC." (PMID 26993610, 2016). "The degree of upregulation when compared to normal tissue was significantly higher in three (POSTN, SERPINB5, TMPRSS4) of five genes than compared to pancreatitis, suggesting that POSTN, SERPINB5 and TMPRSS4 expression increase gradually from healthy pancreas to pancreatitis to PDAC." (PMID 26993610, 2016). "Moreover, we provide the first qRT-PCR-based analysis for enhanced TMPRSS4 expression in microdissected PDAC tissue as compared to pancreatitis or healthy pancreas." (PMID 26993610, 2016).
SARS-CoV infection (1 paper, 2020). "Previous studies indicated that both TMPRSS4 and ST14 facilitate influenza A virus infection but neither had a role in SARS-CoV infection." (PMID 32404436, 2020).
cancer (49 papers, 2012 to 2026). A tumor composed of atypical neoplastic, often pleomorphic cells that invade other tissues. "Recent studies showed that TMPRSS4 is highly expressed in cancer tissues, and its dysregulation has been implicated in tumorigenesis and malignant progress." (PMID 36380313, 2022). "We employed the pan-cancer Kaplan–Meier plotter database and analyzed the association between TMPRSS4 expression and clinical outcome." (PMID 36380313, 2022). "Transmembrane protease serine 4 (TMPRSS4) is a cancer-associated protease associated with prognosis in various types of cancer." (PMID 36380313, 2022). "Our data also highlight alveolar and malignant subsets that express the serine proteases TMPRSS2 and TMPRSS4 implicated in lung pathobiology, including cancer, which also act as SARS-CoV-2 coreceptors." (PMID 33809063, 2021). "TMPRSS4 is a novel TTSP that is highly expressed in a variety of cancers where it has been implicated in their pathogenesis and invasion." (PMID 29529050, 2018). "An increased expression of TMPRSS4 was associated with increased progression and metastatic potential of several cancers." (PMID 26889029, 2016). "Expression of the serine protease TMPRSS4 is highly increased in a variety of solid tumors and is associated with poor prognosis in some cancer types such as breast, colon, cervix, thyroid and liver." (PMID 26989022, 2016). "The pooled results from these different types of cancer demonstrated that high TMPRSS4 expression was significantly associated with patients' poor OS and short TTP." (PMID 27344186, 2016). "TMPRSS4 has been implicated in the induction of epithelial-mesenchymal transitions and in cancer metastasis." (PMID 22692880, 2012). "Given the role of ACE2,TMPRSS2, and TMPRSS4 in providing increased susceptibility to COVID-19in cancer patients, our findings indicate that SLC6A20 might exhibit a similar function." (PMID 37041751, 2023). "This suggests that tumors with high TMPRSS4 expression may be associated with pathways involving cancer cell-ECM crosstalk in NSCLC, in agreement with the prometastatic role of TMPRSS4." (PMID 31659178, 2019). "Associations between TMPRSS2 and TMPRSS4 and cancers have been reported." (PMID 27841306, 2016). "Overall, these results indicate that the cancer-associated TMPRSS4 protein is overexpressed in NSCLC and may represent a potential therapeutic target." (PMID 22692880, 2012). "Therefore, TMPRSS4 expression in a variety of different cancers is associated with poor prognosis and survival, which may be due to an increase in the CSC population." (PMID 37009799, 2023). "A SIGLEC12 variant associated with cancer (Ser458Phe) and a variant found in the general human population (Arg528Trp) attenuate SIGLEC12 cleavage by TMPRSS4." (PMID 41225007, 2026). "TMPRSS4 promotes cancer invasion by activating pro-urokinase-type plasminogen activator (pro-uPA), degrading ECM, and inducing epithelial–mesenchymal transition (EMT)." (PMID 40361374, 2025). "Although there is limited data on TMPRSS2’s role in cancers other than prostate cancer, its interaction with TMPRSS4, known to be overexpressed in several types of cancers, indicates a potential broader role in carcinogenesis." (PMID 39350850, 2024). "This review summarizes up-to-date information regarding the expression, regulation, and clinical relevance of TMPRSS4, as well as its role in pathological contexts, particularly in cancer." (PMID 37009799, 2023). "Based on its broad expression profile in cancer, TMPRSS4 has been the focus of attention in anticancer research." (PMID 37009799, 2023). "While the physiological function and in vivo substrates of TMPRSS4 remain unidentified, much of our knowledge about TMPRSS4 originates from clinical analysis and cell- and xenograft-based studies showing a correlation with cancer and other diseases." (PMID 37009799, 2023).
cancer (continued). "The transmembrane protease serine 4 (TMPRSS4), a member of the TTSP family, is upregulated in pancreatic, colorectal, gastric, lung, thyroid, prostate, and several other cancers; indeed, elevated expression of TMPRSS4 often correlates with poor prognosis." (PMID 37009799, 2023). "Transmembrane protease serine 4 (TMPRSS4) is upregulated in a broad spectrum of cancers and its biological effects on HCC have been evaluated." (PMID 38139236, 2023). "As a result, three genes, SH3BGRL2, TJP3 and TRIM31, were positively correlated with TMPRSS2 and TMPRSS4 for all cancer cell lines and showed distinct differential expression profiles across GI solid tumors." (PMID 35970857, 2022). "Multivariate analysis demonstrated that TMPRSS4 expression and the stage of cancer were crucial prognostic factors for RFS." (PMID 34379296, 2022). "Transmembrane serine protease 4 (TMPRSS4) belongs to the family of type II transmembrane serine proteases that are known to be upregulated in many malignant tumors." (PMID 34379296, 2022). "In NCSLC, TMPRSS4 can trigger cancer cell invasion and metastasis via the TMPRSS4/miR-205/ITG-a5 axis." (PMID 36380313, 2022). "SLUG and TWIST1, master EMT-inducing transcription factors, made essential contributions to TMPRSS4-mediated cancer stem cell (CSC) features through upregulation of SOX2." (PMID 34809669, 2021). "TMPRSS4 induces urokinase-type plasminogen activator (uPA) expression in cancer cells and promotes tumor cell invasion." (PMID 34281234, 2021). "TMPRSS4 was found to be overexpressed in multiple human malignancies such as thyroid, lung, breast, pancreatic, gastric, colon, and other cancers." (PMID 33816264, 2021). "Targeting TMPRSS4 represents a potential approach to anti-cancer therapy aimed at suppressing tumor growth, metastasis, and drug resistance/relapse by suppressing CSC traits." (PMID 34809669, 2021). "This confirms the implication of TMPRSS4 in cancer progression and can make TMPRSS4 to be considered as a potential therapeutic target for Cancer Gene Therapy (CGT)." (PMID 31244309, 2019). "In this study, we report that TMPRSS4 upregulates bcl-2 and survivin to enhance cancer cell survival, and inhibits anoikis and drug treatment sensitivity, potentially via upregulation of AP-1, Sp1, and NF-κB." (PMID 31292507, 2019). "Altogether, this study demonstrates that TMPRSS4 is indeed a potential molecular target for anti-cancer therapy and recommends the development of KRT1853 as a novel anti-cancer agent." (PMID 31292507, 2019). "In summary, we evaluated two novel 2-hydroxydiarylamide derivatives as potential therapeutics against TMPRSS4-positive cancer cells." (PMID 31292507, 2019). "It is intriguing that TMPRSS4 modulates cancer cell survival, proliferation, and invasion potentially through activation of major transcription factors." (PMID 31292507, 2019). "TMPRSS4 provides cancer stem cell (CSC) properties to lung tumor cells and makes them resistant to chemotherapy." (PMID 31817025, 2019). "TMPRSS4 is a member of TTPs and is often overexpressed in many types of cancer tissues such as pancreatic, thyroid, colon, lung, gastric, breast and other cancer tissues, with a poor clinical prognostic." (PMID 31244309, 2019). "We expect that the primary target of KRT1853 and IMD-0354 in cancer cells used in the study is TMPRSS4 for two reason." (PMID 31292507, 2019). "It has been shown that TMPRSS4 inhibition reduced cancer cell proliferation ability by promoting cell cycle arrested, cell apoptosis and enhanced radiotherapy effectiveness." (PMID 31870109, 2019). "It has been reported that TMPRSS4 silencing reduced cancer proliferation and its overexpression induction increases cell proliferation in many kinds of cancer cell lines." (PMID 31244309, 2019). "TMPRSS4 is a novel Type II transmembrane serine protease found at the surface of the cells and is involved in the development and cancer progression." (PMID 31244309, 2019).
cancer (continued). "Together, these results suggest that TMPRSS4 promotes cancer cell survival and drug resistance, potentially through upregulation of bcl-2 and survivin." (PMID 31292507, 2019). "Further evaluation of the anti-tumor activity of these compounds against TMPRSS4-positive cancers in vivo is warranted." (PMID 31292507, 2019). "IMD-0354 and its derivative KRT1853 displayed reduced TMPRSS4-mediated signaling activity, leading to suppression of invasion, proliferation, and survival of cancer cells." (PMID 31292507, 2019). "TMPRSS4 was classified as one of the genes forming a set of markers that distinguish between benign and malignant tumors." (PMID 30089490, 2018). "Transmembrane protease serine 4 (TMPRSS4), a type-II transmembrane serine protease, is frequently upregulated in human cancers." (PMID 28350359, 2017). "We also found that TMPRSS4 activates the transcription factor activating protein-1 (AP-1) to induce cancer cell invasion." (PMID 27385093, 2016). "Most of the classifier genes (TMPRSS4, POSTN, SERPINB5) have been linked to migration, invasion, adhesion and metastasis of PDAC or other cancers, specifically associated with extracellular matrix and tumor microenvironment." (PMID 26993610, 2016). "Further, multiple studies have implied that elevated TMPRSS4 expression in tumor tissues was correlated with poor survival of cancer patients." (PMID 27344186, 2016). "Among them, FAK and Rac1 activation was required for TMPRSS4-mediated cancer cell invasion and epithelial to mesenchymal transition (EMT)." (PMID 27344186, 2016). "TMPRSS4 expression correlates with the metastatic potential of several cancer cell lines, and our cell-based studies demonstrate that TMPRSS4 induces migration, invasion and anchorage-independent growth." (PMID 26993610, 2016). "TMPRSS4 is a novel type II transmembrane serine protease found at the cell surface that is highly expressed in pancreatic, colon, and other cancer tissues." (PMID 27385093, 2016). "Our study suggests that cancer cells can drastically accelerate the aggressiveness of a malignancy by themselves via TMPRSS4-mediated upregulation of Slug and AP-1 and the simultaneous acquirement of a proliferative and invasive phenotype." (PMID 27385093, 2016). "Upregulation of CAP2/Tmprss4 is observed in various cancer types originating from pancreas, lung, breast, colon and stomach, and was found associated with poor prognosis in patients." (PMID 26309024, 2015). "TMPRSS4 expression is upregulated in malignant tumors compared to benign neoplasm or normal tissues, and therefore is suggested as both a diagnostic and prognostic marker for cancers." (PMID 26190376, 2015). "Studies of biological activity have reported that elevated TMPRSS4 expression induced epithelial to mesenchymal transition (EMT) of cancer cells and promoted metastasis." (PMID 22692880, 2012). "Notably, similar to the cancer-associated Ser458Phe variant, the Arg528Trp mutation blocked SIGLEC12 cleavage by TMPRSS4." (PMID 41225007, 2026). "Among these genes, the most overexpressed in platelet-educated cancer cells are those encoding proteins involved in cancer progression and metastasis, including SERPINE1 (358%), MMP2 (297%), MMP10 (214%), TIMP1 (187%), FN1 (166%), TMPRSS4 (146%) and RHOC (102%)." (PMID 40096084, 2025). "Other relevant anticancer siRNA targets include survivin, IL‐10, or transmembrane serine protease 4 (TMPRSS4), which may play a role in cancer cell survival, metastasis, migration, and adhesion." (PMID 38435821, 2024). "Elevated expression of TMPRSS4 correlates with poor prognosis of patients in various cancers." (PMID 37009799, 2023). "Surprisingly, the prognostic role of TMPRSS4 in LUSC by pan-cancer Kaplan-Meier plotter was opposite to the literature, which was attributed to data collection method of different dataset, complex clinical context, diverse tumor environment or altered underlying molecular mechanism." (PMID 36380313, 2022).